LINC02753 (long independently transcribed non-coding RNA 2753)
Synonyms: AP003555.1; onclncRNA-626
Gene: Long non-coding RNA gene on chromosome 11 (70,056,230 to 70,065,371, reverse strand). Ensembl gene ENSG00000248844.
Diseases named in the same sentence as LINC02753 in open-access papers:
LINC02753 is named in the same sentence as 2 diseases in open-access papers, as found by Europe PMC text mining. Sharing a sentence is not in itself a finding about the gene and the disease.
LINC02753 shares sentences with these, for which no sentence is quoted: Colon cancer (2 papers); cancer (1).